KLF2 (KLF transcription factor 2)
Diseases named in the same sentence as KLF2 in open-access papers (continued):
Sharing a sentence is not in itself a finding about the gene and the disease.
cancer (continued). "Because fractionated radiation is routinely used during cancer radiotherapy, we decided to delineate the effects of radiation dose fractionation on the KLF2 signaling cascade at early time points (up to 24 h)." (PMID 32382091, 2020). "Previous studies have shown KLF2 expression is downregulated in many human cancers, such as ovarian, prostate and lung cancer." (PMID 29245984, 2017). "According to a recent report, decreased expression of KLF2 in human cancer was attributed to epigenetic silencing by the histone methyltransferase EZH2." (PMID 29245984, 2017). "It is worth noting that KLF2 inhibited cancer cell invasion and migration, and induced apoptosis and cell cycle arrest even with the absence of RA." (PMID 26416422, 2015). "KLF2 promoter is also an EZH2 target gene in many cancers and recently shown to be hyper-methylated by DNMT1 in endothelial cells." (PMID 25115397, 2014). "Interestingly, another transcription factor, Klf2, was found to have the highest activity in mid scored cells and is a well-known repressor of metastasis in multiple cancer types." (PMID 39748426, 2025). "In addition to various biological functions, KLF2 has been shown to be involved in progression of various cancers." (PMID 38874684, 2024). "The product of another gene, KLF2, a member of Kruppel-like transcriptional factors, is known for its growth inhibitory and apoptosis induction properties and its expression suppression has been reported in many types of cancer." (PMID 38978053, 2024). "Interestingly, KLF2 has a suppressive function in many cancers, including PCa, implying that miR-15b-3p promotes PCa progression by inhibiting KLF2." (PMID 38495481, 2024). "In leukemia T cells, KLF2 is found to weaken the survival of cancer cells." (PMID 37256177, 2023). "Patients with low KLF2 expression levels exhibited poor prognosis across multiple cancer types." (PMID 37123417, 2023). "The Human Protein Atlas was utilized to evaluate KLF2 expression in various cancers." (PMID 37123417, 2023). "The mRNA expression differences of KLF2 in various cancers were analyzed using the TIMER tool." (PMID 37123417, 2023). "KLF2 affects the proliferative ability of cancer cells by modulating the FABP5/PPARγ axis." (PMID 37256177, 2023). "Interestingly, cyclin-dependent kinase 4, with high importance in cancer immunity, was the highest abundant interaction among the novel, gained interactions of the mutant KLF2." (PMID 36466816, 2022). "For example, cancer-derived exosomal hsa-miR-25-3p can mediate the formation of pre-metastatic niche by inducing angiogenesis and vascular permeability through silencing KLF2 and KLF4, thereby promoting CRC metastasis." (PMID 35096570, 2021). "The mechanism(s) by which KLF2 regulates the growth and oncogenic properties of carcinoma cells remain incompletely understood but it was reported that the factor inhibits the expression of epidermal growth factor receptor and that it suppresses KRAS-induced oncogenic transformation." (PMID 26416422, 2015). "In addition, KLF2 is involved in the inhibition of proliferation and migration and is silenced in cancer by the Polycomb repressive complex 2 protein EZH2." (PMID 23565812, 2013). "In addition, researches have reported that KLF2 is significantly dysregulated in many solid malignancies, including gastric cancer, non-small-cell lung cancer, pancreatic ductal adenocarcinoma and prognostic cancer." (PMID 37386390, 2023).
cancer (continued). "Furthermore, KLF2, as an ERK5 downstream target, could be implicated in cancer through different mechanisms that remain unexplored, as could be the case of stem cell biology or other processes such as inflammatory response, immune response, or angiogenesis." (PMID 35884568, 2022). "As such, mutations triggering the expression of this molecule or mutations in its master regulator, Kruppel-like factor 2 (KLF2)—both of which were found in MZL—could be related to the generation of atypical MZ, leading to the development of this type of cancer." (PMID 35328792, 2022). "We focused on KLF2 (Krüppel-Like Factor 2), ETS2 (ETS Proto-Oncogene 2), and EBF1 (Early B Cell Factor 1), which are usually deregulated in several cancers, including BC, and have several putative binding sites on the EGFL7 gene." (PMID 39796183, 2025). "Expression of KLF2 and KLF6 has previously been shown to increase in cancer cells following treatment with the lipophilic statin lovastatin and an association between induction of these genes and apoptosis has been demonstrated." (PMID 36803614, 2023). "Dysregulation of KLF2 and KLF15 has been reported to play vital roles in a variety of human cancers." (PMID 35033064, 2022). "KLF2 was stably expressed in HCCLM3 cells and thus reduced TGF-β-induced wound healing and cancer cell mobility by intervening TGF-β-stimulated promotion of MMP2." (PMID 35992798, 2022). "In nonsmall cell lung carcinoma, LINC01133 suppresses the transcription of KLF2, P21, and E‐cadherin by binding to EZH2 and LSD1, resulting in increased cancer cell growth and invasion." (PMID 34047479, 2021). "Krüppel-like factor 2 (KLF2), is described as a mechanosensitive transcription factor, hence can be activated by physical triggers, and was recently shown to inhibit cell migration in various forms of cancers." (PMID 36214828, 2023). "We showed that TUG1 may regulates the proliferation ability of HCC cells partially through sliencing of the KLF2 by binding with PRC2, which suggested that lncRNAs contribute to different cancer cells biological function through regulating different genes." (PMID 26336870, 2015). "Similarly, EdU results revealed that silencing of KLF2 and CDKN2B could partially rescue SNHG1 knockdown induced reductions in cancer cell proliferative capacity." (PMID 30266084, 2018). "Other predicted blood-secretory marker proteins such as PAICS, CHRDL1, KLF2, COL10A1 and MYL9 have not heretofore been reported to be cancer related." (PMID 21060876, 2010).
infection (22 papers, 2014 to 2025). The state of being infected such as from the introduction of a foreign agent such as serum, vaccine, antigenic substance or organism. "In the presence of insulin in the culture medium, Klf2 increased the protein level of SCAP in primary hepatocytes after 48 h after Ad-ALB-Klf2 infection." (PMID 37949368, 2024). "In this review, we focus on the role of KLF2 in immune cell migration and adhesion in immune cell homeostasis, as well as in immune cell migration during infections and under disease conditions." (PMID 34696279, 2021). "KLF2 and 4 represent one such example whose expression is decreased by noxious stimuli (e.g., infection, inflammatory metabolites, etc) in both cell populations, allowing a concerted response against threat." (PMID 34079826, 2021). "The intracellular protein level of MIF was significantly reduced in ECs infected with adenovirus-KLF2 compared to the one with adenovirus-GFP infection by Western blotting." (PMID 29403061, 2018). "CCR7, Foxo1 and Foxo3a are also known transcriptional targets of Foxo1 or Foxo1 plus KLF2, and their mRNA levels remained unchanged during productive infection." (PMID 25330112, 2014). "Forty-eight hours upon infection, most of the control-infected cells (94%) were continuously growing and consequently lost the eFlour670 dye (region 3), whereas KLF2-transduced cells showed higher levels of eFlour670 fluorescence." (PMID 24874925, 2014). "In order to investigate the effect of statins on the expression of infection-responsive, immunomodulatory genes, 5 genes previously shown to be induced during P. aeruginosa infection were selected for analysis; KLF2, KLF6, IL-8, TLR5 and CCL20." (PMID 25010049, 2014). "Timecourse studies in primary human CD4+ T cells following infection with the HIV reporter virus indicated that the level of KLF2 was significantly upregulated at 24 hpi and showed further increase at 48 hpi, reaching levels comparable to those in resting memory cells." (PMID 41006834, 2025). "We quantified KLF2-GFP+ donor SMARTA cells within the white pulp (constrained by CD169+ marginal zone) or red pulp (outside marginal zone-constrained follicles) by microscopy at day 3.5 post infection." (PMID 39257976, 2024). "While transient downregulation of these factors is essential in acute activation (e.g., fighting infection), the resolution and subsequent maintenance of proper KLF2/4 expression is vital in preventing consequences of long-term myeloid and endothelial activation." (PMID 34079826, 2021). "Stable populations of Tmem cells remain present in the peripheral organs after the clearance of an infection due to KLF2 downregulation, leading to an active form of CD69 which blocks S1PR1 function by conformational changes due to CD69/S1PR1 binding and an inhibition of S1PR1 expression." (PMID 34696279, 2021). "In addition, a strong correlation between the activation status of CD4+ T cells, in which a direct regulation of CCR5 in resting cells by KLF2 was demonstrated, and the susceptibility of an HIV-1 (R5) infection was observed." (PMID 34696279, 2021). "We summarize the key functions of KLF2 in the regulation of chemokine receptors and adhesion molecules and discuss the relevance of the KLF2-mediated control of immune cell migration in the context of immune responses, infections, and diseases." (PMID 34696279, 2021). "Under conditions of infection with WT V. vulnificus, HT-29 cells upregulated KLF2, KLF4, and KLF6 and downregulated NLRP3, TLR4, and CXCR4, suggesting that the MARTX toxin interrupts inflammatory responses, NF-κB signaling, and mitogen-activated protein kinase (MAPK) signaling in infected cells." (PMID 32817457, 2020). "Likewise, infection with KLF2 shRNA lentivirus all reduced KLF2 expression in MGC-803 cells, especially shRNA 1#, compared with cells infected with the scrambled virus." (PMID 29245984, 2017).
infection (continued). "Indeed, we found a highly significant increase in the frequency of GFP+/AnnexinV+ cells 24 h, 48 h and 72 h after infection with KLF2, as measured by flow cytometry." (PMID 24874925, 2014). "The role of KLF6 in infections is currently less clear than that of KLF2." (PMID 25010049, 2014). "The half-life of CD62L mRNA is long and our unpublished data indicate that CD62L persists on the resting T cell surface for several days, so further studies will be required to reveal the kinetics of Foxo1, KLF2 and CD62L mRNA suppression after infection." (PMID 25330112, 2014). "Given that KLF2 is involved in immune cell trafficking and adhesion, we used CellChat (v2.1.1) to identify altered ligand–receptor interactions between HIV-1-infected CD4+ T cells and innate immune cells during infection." (PMID 40838493, 2025). "An increased number of KLF2-GFP+ donor SMARTA T cells were found within the white pulp but not the red pulp of mice depleted of NK cells prior to infection in comparison to non-depleted controls." (PMID 39257976, 2024). "We found three genes that were commonly activated with infection with SCV2 at both 12 and 24 hpi (DUSP1, HES1, KLF2) and some non-congruent genes at 12 hpi (CCL5, ZBP1, NRXN2, STAB1, SLC25A47, CXCL11) and 24 hpi (FOXA2, RHOB)." (PMID 37504520, 2023).
cardiovascular disease (20 papers, 2013 to 2026). "Although the beneficial effect of KLF2-EVs on cardiovascular disease has been identified, the underlying functions and mechanisms in DCM have not been extensively studied." (PMID 35139878, 2022). "THBD and KLF2 transcripts, associated with ’Cardiovascular disease’ by IPA analysis, were up-modulated in 2 of 3 EGF-stimulated EOC cells." (PMID 23889749, 2013). "The observations presented here reveal that TA is a novel KLF2 activator and suggest that KLF2 could serve as a promising therapeutic target for the treatment of endothelial inflammation-associated cardiovascular disease." (PMID 28751752, 2017). "These risk factors have in common reduced expression of Krüppel-like factors 2 and 4 (KLF2/4), the endothelial transcription factors that protect against cardiovascular disease." (PMID 41959392, 2026). "Given its importance in maintaining a healthy endothelium, we sought to identify endothelial regulators of the KLF2 transcriptional program as potential new therapeutic approaches to treating cardiovascular disease." (PMID 37363403, 2023). "Finally, we looked at the effect of GPR30 agonism on expression of KLF2, a key protector against cardiovascular disease." (PMID 33875621, 2021). "Induction of TM and KLF2 may be a promising strategy to treat inflammatory, coagulation, septic, and cardiovascular disorders." (PMID 27869747, 2016). "The association of progenitor cells with cardiovascular disease has been the subject of intensive investigations, and enhanced proliferation of EPC as a result of exposure to uniform shear stress and overexpression of KLF2 have been reported." (PMID 22903503, 2013). "Therefore, KLF2 might be a promising target for the treatment of cardiovascular diseases." (PMID 33946046, 2021). "Interestingly, although KLF2 is known to suppress VCAM-1 and ICAM-1 expression under physiological conditions, we observed increased VCAM-1 mRNA expression, consistent with a proinflammatory endothelial phenotype commonly observed in cardiovascular disease." (PMID 41562845, 2026).
inflammation (5 papers, 2013 to 2025). Aberrant reaction of the microcirculation characterized by movement of fluid and leukocytes from the blood into extravascular tissues. "We further show using KLF2 shRNA that the inhibitory effect of NMP on endothelial inflammation and subsequent monocyte adhesion is KLF2 dependent." (PMID 32669659, 2020). "In the present study, we provide evidence that TA induces endothelial KLF2 expression and thereby attenuates vascular endothelial inflammation." (PMID 28751752, 2017). "Both KLF2 and KLF4 have previously been reported in vascular inflammation and as targets of miR-92a." (PMID 36768805, 2023).
bacterial infections (4 papers, 2014 to 2021). "Previous studies utilizing Lyz2cre-Klf2fl/fl mice analyzed the function of KLF2 in combating bacterial infections by innate cells." (PMID 27302755, 2016). "The deletion of KLF2 in all myeloid cells by the use of the Lyz2-cre deleter identified KLF2 as a central regulator of innate immune responses to bacterial infections and septic shock (Table A1) and connected KLF2 expression to hypoxia, HIF-1α and NF-κB signaling networks." (PMID 34696279, 2021). "KLF2 inhibits monocyte activation by inhibiting NFκB activity, which correlates with decreased expression of multiple cytokines and HIF1α, a TF that regulates myeloid cell response to bacterial infection and reactive oxygen species." (PMID 25099603, 2014).
kidney disease (3 papers, 2019 to 2023). "The expression of KLF2 in ECs confers endothelial integrity by regulating anti-inflammatory and antithrombotic effects, while reduced transcriptional activity of KLF2 exacerbates chronic inflammation and endothelial damage in renal diseases." (PMID 37795100, 2023). "Decreased KLF2 was reported to increase glomerular endothelial cell injury as well as kidney disease in a mouse model with unilateral nephrectomy." (PMID 34462420, 2021). "Although several KLF members including KLF2, KLF4, KLF6, and KLF15 in glomerular endothelial cells or podocytes have been linked to kidney diseases, all these reported KLF members serve as renal protectors." (PMID 30948420, 2019).
metabolic disease (3 papers, 2020 to 2025). A congenital disorder (due to inherited enzyme abnormality) or acquired (due to failure of a metabolically important organ) disorder resulting from an abnormal metabolic process. "Consistently, ablation of K2KO microglia significantly impacted weight gain and glucose homeostasis, underscoring that microglial activation via loss of KLF2 drives CNS-mediated metabolic disease." (PMID 33208733, 2020). "Peripheral K2KO myeloid cells also contribute to dysregulated glucose homeostasis as evidenced by IPGTT and IPITT, further underscoring a substantial role for peripheral loss of myeloid KLF2 in metabolic disease." (PMID 33208733, 2020). "Together, these results demonstrate that loss of KLF2 in myeloid cells confers a strong propensity towards metabolic disease under basal and an excess nutrient states." (PMID 33208733, 2020). "To determine if loss of myeloid KLF2 conferred susceptibility to metabolic disease in vivo, we first characterized the metabolic phenotype of the K2KO mice at baseline." (PMID 33208733, 2020). "Concurrently, peripheral loss of myeloid KLF2 contributes to metabolic disease." (PMID 33208733, 2020). "To examine whether loss of KLF2 in peripheral, hematopoietically-derived myeloid cells contributes to metabolic disease, we generated bone marrow chimera mice in which central myeloid cells were spared from radiation using head shielding." (PMID 33208733, 2020). "Much like its endothelial counterpart, myeloid KLF2 levels are sensitive to inflammatory stimuli and are decreased in acute and chronic inflammatory states such as sepsis, coronary artery disease, and metabolic disease." (PMID 34079826, 2021). "To determine the extent to which central myeloid cells and feeding behavior contribute to the development of metabolic disease in the context of KLF2 deletion, we employed two methods of central nervous system (CNS) macrophage manipulation." (PMID 33208733, 2020). "Given the robust microglial response seen in K2KO mice, we believe that KLF2 serves to regulate aberrant activation of hypothalamic microglia, thereby protecting against centrally derived metabolic disease." (PMID 33208733, 2020). "Finally, sustained overexpression of KLF2 in myeloid cells protects against both central and peripheral metaflammation and metabolic disease." (PMID 33208733, 2020). "Our data suggest that downregulation of myeloid KLF2 may serve as a metaflammatory switch that triggers metabolic disease in response to HFD." (PMID 33208733, 2020). "Finally, we use a myeloid KLF2 overexpressing mouse to demonstrate protection against diet-induced metabolic disease." (PMID 33208733, 2020). "Loss of myeloid KLF2 caused mice to exhibit early stages of metabolic disease without HFD stimulation, demonstrating the importance of this factor in maintaining homeostatic control over metaflammation." (PMID 33208733, 2020). "Here the authors report that deletion of the transcription factor KLF2 in myeloid cells leads to increased feeding and weight gain in mice with concomitant peripheral and central tissue inflammation, while overexpression protects against diet-induced metabolic disease." (PMID 33208733, 2020).
cardiac diseases (1 paper, 2022). "Identifying a neutrophil/KLF2/NETosis/thrombosis pathway for chronic nonischemic cardiac diseases provides pathogenic mechanisms and promising therapeutic targets for HF." (PMID 34793333, 2022).
hematologic malignancies (1 paper, 2022). "KLF2, a member of the zinc finger family, has been illustrated to be involved in the pathology of hematologic malignancies." (PMID 34635968, 2022).